LAMP1 (lysosome associated membrane protein 1)
Diseases named in the same sentence as LAMP1 in open-access papers (continued):
Sharing a sentence is not in itself a finding about the gene and the disease.
pancreatic cancer (21 papers, 2013 to 2025). "Nevertheless, our data indicate that UBL4A suppresses pancreatic cancer development by directly regulating LAMP1." (PMID 31288830, 2019). "The current data provide greater insights into the function of the UBL4A/LAMP1 autophagy axis in the aggressive progression of pancreatic cancer." (PMID 31288830, 2019). "Our findings suggest a new mechanism for the regulation of proliferation and metastasis by the UBL4A/LAMP1/autophagy axis in pancreatic cancer and reveal a direct interaction between UBL4A and LAMP1." (PMID 31288830, 2019). "Together, these data indicate that LAMP1 restoration in pancreatic cancer cells reverses the UBL4A-induced antitumor effects and inhibition of autophagy." (PMID 31288830, 2019). "High LAMP1 expression has been found in cancer development, progression tumor metastasis in astrocytoma, colorectal cancer, pancreatic carcinoma and various other cancer tissues." (PMID 31425520, 2019). "However, contrary to these findings, pancreatic cancer patients with high mRNA levels of LAMP1 exhibited significantly prolonged survival after tumor resection compared to those with low to moderate mRNA expression levels." (PMID 39669571, 2024). "Furthermore, UBL4A caused lysosomal dysfunction by directly interacting with LAMP1, and LAMP1 overexpression reversed the antitumor effects of UBL4A in pancreatic cancer." (PMID 31288830, 2019). "Moreover, increased expression of UBL4A caused increased levels of LAMP1, LC3B, p62, and E-cadherin and resulted in decreased levels of CTSB, vimentin, and N-cadherin in the orthotopic pancreatic cancer models." (PMID 31288830, 2019). "For instance, in some human pancreatic cancer cells, connexons formed by Cx43 fail to form gap junctions because they undergo endocytosis prior to gap junction assembly and instead localize in cytoplasmic vesicular compartments, many of which are LAMP1 positive." (PMID 38597989, 2024). "Further, our results illustrated that SDS-203 treatment failed to overexpress LC3-II and LAMP-1 expression in transiently mTORC1 upregulated pancreatic cancer cells compared to control." (PMID 35322026, 2022). "Additionally, immunohistochemical results showed that the UBL4A level was positively correlated with the expression of LAMP1, LC3B, p62, and E-cadherin and negatively correlated with CTSB, vimentin, and N-cadherin in pancreatic cancer patients." (PMID 31288830, 2019). "Both LAMP1 and ORP150 showed over-expressions in pancreatic tumor cells (P-value = 0.0014)." (PMID 25987888, 2015). "Lysosome-associated membrane glycoprotein 1(LAMP1) and hypoxia up-regulated protein 1 (ORP 150) were chosen for analysis in this regard because they previously have not been associated with pancreatic cancer." (PMID 25987888, 2015). "Therefore, we tried an alternative approach that we consider to be more stringent by analyzing clinical samples for two proteins (LAMP1 and ORP150) not previously associated with pancreatic cancer and found preferential expression in tumors compared to normal tissue in both cases." (PMID 25987888, 2015). "The protein expression of LAMP1 and ORP150 was investigated by immunohistochemistry in eight pairs of pancreatic cancer and matched non-tumorous pancreas tissue sections." (PMID 25987888, 2015).
colon carcinoma (16 papers, 2017 to 2025). "We stimulated human primary blood-borne NK cells pre-treated with different cytokine regimens with the HCT116 human colon cancer cell line and used detection of lysosome-associated membrane glycoprotein 1 (LAMP1) as an identifier of rapid NK cell degranulation." (PMID 40155684, 2025). "Colon cancer cells with strong metastatic ability express higher levels of LAMP1 protein on their surface, and it has been demonstrated that LAMP1 binds to E-selectin through terminal sialylated Lewis oligosaccharide -X (SLeX), promoting colon cancer cell metastasis." (PMID 39669571, 2024). "The expression of LAMP-1 occurred on the surface of various cancer cells, such as colon cancer." (PMID 31799198, 2019). "In particular, metastatic colon cancer cells are characterized by high levels of LAMP1 mRNA in relation to cells with low metastatic potential, which may indicate the participation of LAMP1 in cell adhesion and migration." (PMID 30344951, 2018). "In colon cancer, the E-selectin ligands identified so far are HCELL, carcinoembryonic antigen (CEA), podocalyxin-like protein (PCLP), LAMP-1 (lysosomal membrane glycoprotein-1) and LAMP-2." (PMID 33167483, 2020). "In conclusion, our study presents compelling evidence that LAMP1 holds significant promise as a biomarker for the non-invasive imaging of a diverse carcinomas, particularly breast and colon cancers." (PMID 40872517, 2025). "Indeed, lysosomal membrane proteins, LAMP-1 and LAMP-2, have been identified in Colo-205 cell lines as E-selectin ligands and their expression levels mediated colon cancer cells adhesion to E-selectin." (PMID 33167483, 2020). "Using affinity chromatography on GAL-1-agarose columns and immunoprecipitation, LAMP-1 and LAMP-2 were first identified as candidate GAL-1 receptors in Chinese Hamster Ovary (CHO), human A121 ovarian carcinoma and butyrate-differentiated KM12 colon carcinoma cell membrane extracts." (PMID 37898403, 2023).
ovarian carcinoma (16 papers, 2012 to 2025). A malignant neoplasm originating from the surface ovarian epithelium. "Other studies have explored the association between expression levels of lysosome-associated membrane protein-1 (LAMP1), which protects the lysosomal membrane from intracellular proteolysis, and ovarian cancer progression." (PMID 34503128, 2021). "Under hypoxic conditions, ovarian cancer cells upregulate Rab27a and downregulate Rab7, LAMP1/2, and NEU-1, promoting exosome release." (PMID 39334866, 2024). "Another study examining LAMP1 expression in ovarian cancer patients found that LAMP1 expression was significantly higher in tumor tissues compared to benign or normal tissues." (PMID 34503128, 2021). "Similarly, overexpression of LAMP1 in epithelial ovarian cancer serves as an indicator of unfavorable prognosis for patients." (PMID 39669571, 2024). "Simultaneously, XPR1 and LAMP1 proteins were found to be in the same location in the cytoplasm of SKOV3 and A2780 cells from ovarian cancer." (PMID 40641524, 2025). "Studies have demonstrated that in the ovarian cancer cell line OVCAR3, LAMP1 is upregulated 1.84 times after 24 hours of epidermal growth factor (EGF) treatment but downregulated after 48 hours of exposure." (PMID 39669571, 2024). "Additionally, it was discovered that the levels of LAMP1 protein rose following XPR1 suppression, but decreased with XPR1 up-regulation in SKOV3 and A2780 ovarian cancer cells." (PMID 40641524, 2025). "The results of the present research were in agreement with those of the previous studies illustrating the overexpression of LAMP1 in ovarian cancers and breast tumors, compared to non-cancerous samples." (PMID 35145930, 2022). "Following HULC siRNA transfection of ovarian cancer cells, ATG7, LC3 and LAMP1 mRNA and protein expression both were significantly higher than in the control, whereas expression of SQSTM1 and ITGB1 was significantly decreased by HULC siRNA transfection compared with the negative control (P<0.05)." (PMID 29022892, 2017). "Therefore, we suggest that the lncRNA HULC may cause changes in cell homeostasis by inhibiting autophagy and promoting ovarian cancer by regulating ATG7, LC3, LAMP1 and SQSTM1 expression." (PMID 29022892, 2017).
influenza (15 papers, 2011 to 2024). An acute viral infection of the respiratory tract, occurring in isolated cases, in epidemics, or in pandemics; it is caused by serologically different strains of viruses (influenzaviruses) designated A, B, and C, has a 3-day incubation period, and usually lasts for 3 to 10 days. "A comparison of intracellular IFN-γ levels and CD107a (LAMP1) expression on this subset of NK cells in the WT and NKCKD mice revealed a similar level of response in both mice following influenza infection." (PMID 26928844, 2016).
neuroblastoma (14 papers, 2007 to 2025). Neuroblastoma (NB) is the most common solid, extracranial childhood tumor. "To study this “stop-and-run” alternating behavior, we fluorescently labeled the lysosomal membrane with GFP by tagging the lysosome-associated membrane protein LAMP-1, and we performed 4D tracking on the organelles found at the periphery of living human neuroblastoma SK-N-BE cells." (PMID 39043637, 2024). "While the anti-Lamp-1 co-staining showed the neuroblastoma exosomes inside Lamp-1-positive late endosomes of oligodendrocytes or astrocytes, the exosomes were not present within Lamp-1-positive compartments of neurons." (PMID 34069542, 2021). "As previously documented in neuroblastoma cells in culture, treatment of GBM organotypic cultures with BafA1 increased lysosome-associated membrane protein-1 (LAMP-1) content, indicating induction of lysosomal stress." (PMID 26020805, 2015). "Colocalization of ATG5- and LAMP1-positive endomembranes was also seen in H4 (neuroblastoma) and HCT116 cells." (PMID 25254627, 2014). "Additionally, MPP+ treatment was also found to decrease the LAMP1 level in human dopaminergic BE-M17 neuroblastoma cells, as well as MPTP, treated mice brain." (PMID 32098449, 2020). "In endosomal fractions isolated from squalestatin-treated neuroblastoma cells pulsed with MoPrP105-132 for 1 hour, MoPrP105-132 was detected in the LAMP-1 positive, TfR negative, lysosomal fraction." (PMID 18034899, 2007). "In a differentiated human neuroblastoma cell line (SH-SY5Y), endogenous ClC-6 colocalizes with LAMP-1, a late endosomal/lysosomal marker, but not with early/recycling endosomal markers such as EEA-1 and transferrin receptor." (PMID 17534424, 2007). "Mouse neuroblastoma N2a cells pretreated with LRRK2, AP3B1, or non-targeting siRNA were surface-labeled with an Alexa488-conjugated antibody to the extracellular domain of LAMP1 for 30 min at 4 °C." (PMID 27424887, 2016).
glioblastoma (12 papers, 2011 to 2025). The most malignant astrocytic tumor (WHO grade IV). "In high-grade gliomas (HGG), the cytoplasm and blood vessels of glioblastoma exhibit notable expression of the LAMP1 gene, with significantly higher transcriptional activity compared to normal brain tissue." (PMID 39669571, 2024). "It is possible that the striking increase in LAMP-1 is an indication of the onset of apoptosis, an observation noted in glioblastoma cells in culture." (PMID 21711726, 2011). "In conclusion, BIBF inhibits autophagy and promotes the accumulation of toxic substances in glioblastoma, leading to the onset of apoptosis by decreasing the expression levels of LAMP1, LAMP2, and Rab7 while impairing lysosomal function and its ability to fuse with autophagosomes." (PMID 39859159, 2025). "Recent studies have shown LAMP1 overexpression of both mRNA and protein levels in high-grade glioblastoma multiforme (GBM)." (PMID 32993062, 2020). "They proved that MIPP triggered the formation of vacuoles in glioblastoma cells that expressed markers of late endosomes, such as Rab7 and LAMP1, but did not appear to be lysosomes or autophagosomes." (PMID 38892288, 2024). "Furthermore, in both ras-activated glioblastoma cells and SV40-infected cells, vacuoles contain endosomal markers such as Lamp-1 and undergo extracellular fluid uptake resembling macropinocytosis." (PMID 33028008, 2020). "Although the specific role of LAMP-1 in glioblastoma remains unknown, our results suggest a negative impact of PLEKHG5 depletion followed specifically by a decreased LAMP-1 expression and impaired autolysosome formation on tumour cell survival." (PMID 33318498, 2020).
lymphoma (12 papers, 2013 to 2025). A malignant (clonal) proliferation of B- lymphocytes or T- lymphocytes which involves the lymph nodes, bone marrow and/or extranodal sites. "Our data showed these lymphoma vesicles did not strongly express CD63, LAMP-1, CD9, or TSG101." (PMID 33513976, 2021).
lysosomal storage disease (12 papers, 2012 to 2025). A metabolic disorder caused by mutations in proteins critical for lysosomal function, including lysosomal enzymes, lysosomal integral membrane proteins, and proteins involved in the post-translational modification and trafficking of lysosomal proteins. "Increased levels of the lysosome marker LAMP-1 (lysosome-associated membrane protein-1) often accompany increases in LC3 in models of lysosomal storage diseases or models of induced lysosome dysfunction and suggest a compromise in autophagy completion." (PMID 24529306, 2014). "This phenomenon suggests that BTV infection induces lysosomal disfunctions similar to what is observed in lysosomal storage diseases, commonly associated with an increase of lysosome biogenesis, an increased LAMP1 expression at the cell surface, as well as lysosome enlargement." (PMID 33075107, 2020). "LAMP1 is a lysosomal membrane protein that is stable under normal conditions, but can accumulate during lysosomal storage diseases." (PMID 40098620, 2025). "Together, these data suggest that lysosome enlargement and increased expression of LAMP1 and 2, both common features in other lysosomal storage diseases, were also observed in KD patient-derived fibroblasts." (PMID 27780934, 2016). "Existence of LAMP1 aggregates in myofibers of TSC1mKO mice suggests impaired lysosomal degradation, supported by the presence of inclusions and glycogen accumulation in muscle, characteristic of lysosome storage disease." (PMID 36398408, 2023). "Imaging LAMP1 and LAMP2 revealed lower signals in T1D α cells, but a higher LAMP1/LAMP2 ratio, suggestive of lysosomal disorder." (PMID 41026524, 2025). "The upregulation of LAMP1, lysosomal enzymes (HEXB and NAGLU) as well as autophagy has been found in multiple lysosome storage diseases (LSDs)." (PMID 35215314, 2022). "Since JNCL is a lysosomal storage disorder with alterations in endosomal/lysosomal system, the localization of the intracellular CTX in lysosomes was studied using staining with anti-LAMP-1 antibodies in CTX-A488 labeled WT and Cln3Δex7/8 cells." (PMID 29470438, 2018). "Consistent with a lysosomal storage disorder, the morphology of lysosomes in the AGU fibroblasts was altered as compared to control cells, as also revealed by Lysotracker and LAMP-1 staining." (PMID 27876883, 2016). "Finally, in addition to GRN, we found upregulation of other lysosomal genes frequently dysregulated in lysosomal storage disorders such as NEU1, NPC2, PSAP, CTSD, LAMP1, and HEXA." (PMID 38643236, 2024). "In individuals with lysosomal storage diseases, accumulation of non-metabolized compounds results in an increase in the number and size of lysosomes, and thus an increase in lysosomal proteins, with LAMP-1 levels increasing by up to five-fold." (PMID 29672630, 2018).
Alzheimer disease (11 papers, 2015 to 2025). A progressive, neurodegenerative disease characterized by loss of function and death of nerve cells in several areas of the brain leading to loss of cognitive function such as memory and language. "Furthermore, immunohistochemical studies have shown increased lysosomal‐associated membrane protein 1 (LAMP1) immunoreactivity in neurons, and in glial cells in Alzheimer's disease, indicating that LAMP1 is critical for the phagocytic activity of microglia." (PMID 38649789, 2024). "In Alzheimer Disease (AD), possible biomarkers with diagnostic relevance have been identified, such as elevated lysosome-associated membrane protein 1 (LAMP1) and cathepsin D levels in plasma EVs, and low levels of EV-associated miRNA-193b in cerebrospinal fluid." (PMID 35879759, 2022). "We have also identified and validated Alzheimer’s disease specific markers ectonucleotide pyrophosphatase/phosphodiesterase 2, lysosome-associated membrane protein 1, pro-orexin and transthyretin that have the potential to discriminate Lewy body dementia from Alzheimer’s disease." (PMID 26627638, 2015). "Previous studies have shown that Rab5 activation mediates neuronal apoptosis caused by a familial Alzheimer’s disease (AD) mutant of amyloid precursor protein (APP) and that LAMP1 plays a role in KA-mediated apoptotic neuronal death." (PMID 33445746, 2021). "This is consistent with some prior studies that have shown the presence of lysosomal proteins in isolated exosomes, including cathepsin D and LAMP-1 in exosomes from Alzheimer disease patients and glucocerebrosidase in exosomes from Parkinson’s disease patients." (PMID 30987321, 2019). "LAMP-1, LAMP-2, and LC3 levels are significantly increased in the CSF from patients with Alzheimer’s disease, and the autophagy biomarkers LC3B and Beclin1 correlate with clinical outcomes and disease severity in patients who experienced an acute stroke." (PMID 30442917, 2018).
cervical cancer (11 papers, 2014 to 2025). A primary or metastatic malignant neoplasm involving the cervix. "In cervical cancer, transcriptome sequencing and bioinformatics analysis revealed that LAMP1 acts as a downstream regulator of autophagy and participates in HPV-16E6/E7-mediated regulation of autophagy in cervical cancer cells." (PMID 39669571, 2024). "It is worth noting that HS-27a and HS-5 were obtained from primary hMSCs transformed with Human papillomavirus 16E6/E7, which activates autophagy via Atg9B and LAMP1 in cervical cancer cells." (PMID 32484831, 2020). "Our results suggest that Atg9B and LAMP1, as candidate downstream regulators of 16E6 and 16E7, play a positive role in promoting autophagy flux, as 16E6 and 16E7 do, in cervical cancer cells." (PMID 31215164, 2019). "Our results suggest that Atg9B and LAMP1 overexpressions compensate, at least partially, the autophagic blockage induced by 16E6E7 knockdown in cervical cancer cells." (PMID 31215164, 2019). "Our findings verified that 16E6/E7 activated autophagy via accelerating autophagosome formation and degradation, and Atg9B and LAMP1 were involved in the process of 16E6/E7 modulating autophagy, suggesting that targeting autophagy may be a potential approach in cervical cancer therapeutics." (PMID 31215164, 2019).
glioma (11 papers, 2009 to 2023). A benign or malignant brain and spinal cord tumor that arises from glial cells (astrocytes, oligodendrocytes, ependymal cells). "Mutant IDH1 (IDH1-mut) glioma cells downregulate ICAM1 via ICAM1 promoter methylation resulting in an increased expression of LAMP1 (CD107a), a lysosome-associated membrane protein which has a key role in the formation of phagolysosomes (Molecular event 24)." (PMID 36555253, 2022). "We compared the expression of the lysosome marker LAMP1 between C6 glioma cells and astrocytes by surface staining, and found that LAMP1 was expressed more on the surface of glioma cells than on astrocytes." (PMID 23029308, 2012). "To further support the surface staining result, we carried out a standard FACS assay for LAMP1 on the surface of C6 and U251 cells and astrocytes, and found both glioma cells had more lysosomes on the cell surface than astrocytes, according to the proporation of surface LAMP1 positive cells." (PMID 23029308, 2012). "Interestingly, seven urinary proteins were differentially abundant between glioma and meningioma patients, including AMP4, CD276, LAMP1, NAPSA, LEG1, DNAS1, and BGAL." (PMID 32922940, 2020).
HIV-1 infection (11 papers, 2012 to 2022). The type species of lentivirus and the etiologic agent of acquired immunodeficiency syndrome (AIDS). "An important finding in the current study was that Rab5, −7 and −11 and LAMP1 were significantly upregulated in expression following HIV-1 infection." (PMID 25608975, 2015).